FLCN (folliculin)
Description:
Multi-functional protein, involved in both the cellular response to amino acid availability and in the regulation of glycolysis. GTPase-activating protein that plays a key role in the cellular response to amino acid availability through regulation of the non-canonical mTORC1 signaling cascade controlling the MiT/TFE factors TFEB and TFE3. Activates mTORC1 by acting as a GTPase-activating protein: specifically stimulates GTP hydrolysis by RagC/RRAGC or RagD/RRAGD, promoting the conversion to the GDP-bound state of RagC/RRAGC or RagD/RRAGD, and thereby activating the kinase activity of mTORC1. The GTPase-activating activity is inhibited during starvation and activated in presence of nutrients. Acts as a key component for non-canonical mTORC1-dependent control of the MiT/TFE factors TFEB and TFE3, while it is not involved in mTORC1-dependent phosphorylation of canonical RPS6KB1/S6K1 and EIF4EBP1/4E-BP1. In low-amino acid conditions, the lysosomal folliculin complex (LFC) is formed on the membrane of lysosomes, which inhibits the GTPase-activating activity of FLCN, inactivates mTORC1 and maximizes nuclear translocation of TFEB and TFE3. Upon amino acid restimulation, RagA/RRAGA (or RagB/RRAGB) nucleotide exchange promotes disassembly of the LFC complex and liberates the GTPase-activating activity of FLCN, leading to activation of mTORC1 and subsequent cytoplasmic retention of TFEB and TFE3. Indirectly acts as a positive regulator of Wnt signaling by promoting mTOR-dependent cytoplasmic retention of MiT/TFE factor TFE3. Required for the exit of hematopoietic stem cell from pluripotency by promoting mTOR-dependent cytoplasmic retention of TFE3, thereby increasing Wnt signaling. Acts as an inhibitor of browning of adipose tissue by regulating mTOR-dependent cytoplasmic retention of TFE3 (By similarity). Involved in the control of embryonic stem cells differentiation; together with LAMTOR1 it is necessary to recruit and activate RagC/RRAGC and RagD/RRAGD at the lysosomes, and to induce exit of embryonic stem cells from pluripotency via non-canonical, mTOR-independent TFE3 inactivation (By similarity). In response to flow stress, regulates STK11/LKB1 accumulation and mTORC1 activation through primary cilia: may act by recruiting STK11/LKB1 to primary cilia for activation of AMPK resided at basal bodies, causing mTORC1 down-regulation. Together with FNIP1 and/or FNIP2, regulates autophagy: following phosphorylation by ULK1, interacts with GABARAP and promotes autophagy. Required for starvation-induced perinuclear clustering of lysosomes by promoting association of RILP with its effector RAB34. Regulates glycolysis by binding to lactate dehydrogenase LDHA, acting as an uncompetitive inhibitor.
Synonyms: BHD; MGC17998; MGC23445; DENND8B; FLCL
Tractability: Small molecule: a structure with a bound ligand is known. Antibody: its Gene Ontology location is reachable by antibodies, with high confidence. PROTAC: ubiquitination databases record sites on it; its protein half-life has been measured.
Gene: Protein-coding gene on chromosome 17 (17,212,206 to 17,237,203, reverse strand). Ensembl gene ENSG00000154803.
Subcellular location: Lysosome membrane; Cytoplasm, cytosol; Cell projection, cilium; Cytoplasm, cytoskeleton, microtubule organizing center, centrosome; Cytoplasm, cytoskeleton, spindle; Nucleus
Subcellular location (Human Protein Atlas): Cytosol; Plasma membrane; Vesicles
Pathways (Reactome):
Cellular responses to stimuli: Amino acids regulate mTORC1
Gene Ontology:
Molecular function: enzyme binding; enzyme inhibitor activity; GTPase activator activity; protein binding
Biological process: cellular response to amino acid starvation; cellular response to starvation; intracellular signal transduction; lysosome localization; negative regulation of glycolytic process; negative regulation of lysosome organization; negative regulation of Rho protein signal transduction; negative regulation of transcription by RNA polymerase II; positive regulation of autophagy; positive regulation of TOR signaling; positive regulation of TORC1 signaling; regulation of Ras protein signal transduction; cell-cell junction assembly; energy homeostasis; hemopoiesis; in utero embryonic development; negative regulation of brown fat cell differentiation; negative regulation of cell proliferation involved in kidney development; negative regulation of cold-induced thermogenesis; negative regulation of ERK1 and ERK2 cascade; negative regulation of phosphatidylinositol 3-kinase/protein kinase B signal transduction; negative regulation of TOR signaling; positive regulation of apoptotic process; positive regulation of transforming growth factor beta receptor signaling pathway; regulation of pro-B cell differentiation; and 4 more
Cellular component: cell-cell contact zone; centrosome; cilium; cytoplasm; cytosol; FNIP-folliculin RagC/D GAP; lysosomal membrane; midbody; mitotic spindle; nucleus; lysosome; spindle
Genetic constraint (gnomAD): Loss-of-function variants: 21 observed, 62.05 expected, observed/expected ratio (o/e) 0.34, 90% interval 0.24 to 0.49. The upper end of that interval is the gene's LOEUF score, 0.49, which puts it in group 2 of 6, group 1 being the genes least tolerant of losing a copy. Missense variants: 657 observed, 810.31 expected, observed/expected ratio (o/e) 0.81, 90% interval 0.76 to 0.87. Synonymous variants: 319 observed, 323.18 expected, observed/expected ratio (o/e) 0.99, 90% interval 0.9 to 1.08.
Homologues: Orthologues: chimpanzee FLCN (99% identical), macaque FLCN (99% identical), guinea pig FLCN (95% identical), dog FLCN (94% identical), rat Flcn (93% identical), mouse Flcn (93% identical), pig FLCN (91% identical), rabbit FLCN (91% identical), tropical clawed frog flcn (82% identical), zebrafish flcn (61% identical), Caenorhabditis elegans flcn-1 (25% identical), Drosophila melanogaster BHD (24% identical).
Diseases named in the same sentence as FLCN in open-access papers:
FLCN is named in the same sentence as 146 diseases in open-access papers, as found by Europe PMC text mining. Sharing a sentence is not in itself a finding about the gene and the disease. The quoted sentences say what the papers report.
Birt-Hogg-Dube syndrome (85 papers, 2008 to 2026). "Loss-of-function mutations in FLCN lead to Birt-Hogg-Dubé syndrome in humans, a rare inherited disease characterized by skin tumors and renal cysts." (PMID 41477847, 2026). "Birt-Hogg-Dubé syndrome (BHDS) is a hereditary cancer syndrome caused by pathogenic variants in the FLCN gene." (PMID 42278264, 2026). "Birt-Hogg-Dubé syndrome (BHDS) is a rare autosomal dominant disorder caused by mutations in the FLCN gene, which encodes folliculin, a tumor suppressor protein involved in cellular energy regulation and mTOR (mammalian target of rapamycin) signaling pathways." (PMID 40589676, 2025). "Birt-Hogg-Dubé syndrome (BHDS) is a rare autosomal dominant genodermatosis caused by mutations in the folliculin (FLCN) gene on chromosome 17p11.2." (PMID 40575199, 2025). "Birt-Hogg-Dubé syndrome (BHDS) is a rare autosomal dominant disorder caused by mutations in the folliculin (FLCN) gene, characterized by a clinical triad of pulmonary cysts with spontaneous pneumothorax, cutaneous fibrofolliculomas, and renal tumors." (PMID 40575199, 2025). "On the other hand, the FLCN gene is associated with Birt-Hogg-Dubé syndrome and increases the risk of CRC." (PMID 40458721, 2025). "Folliculin (FLCN) is a highly conserved protein first identified in 2002 as the causative gene of Birt-Hogg-Dubé syndrome." (PMID 40449101, 2025). "Birt-Hogg-Dubé syndrome (BHD) is a rare autosomal dominant disorder caused by germline mutations in the folliculin (FLCN) gene." (PMID 39300538, 2024). "Birt-Hogg-Dubé syndrome (BHD syndrome) is an autosomal dominant multisystem disorder with variable expression due to pathogenic constitutional variants in the FLCN gene." (PMID 39085584, 2024). "Germline loss-of-function mutations in mTOR pathway gene FLCN in Birt-Hogg-Dubé syndrome predispose not only to chRCC and RO, but also to more aggressive clear cell and papillary RCCs." (PMID 39271965, 2024). "Multifocal and bilateral tumours are known to be associated with the Birt-Hogg-Dube syndrome where it shows the FLCN mutation and checkerboard mosaic pattern on morphology." (PMID 38265103, 2024). "Both of these tumour types, thought to be derived from collecting duct type A cells, are almost exclusively diagnosed in older adults, even with the presence of a predisposing germline mutation in mTOR pathway gene FLCN (Birt-Hogg-Dubé syndrome)." (PMID 39271965, 2024). "In previous reports, FLCN gene mutations in BHD syndrome in China differed from those in Europe and the United States." (PMID 39300538, 2024). "Birt-Hogg-Dubé syndrome (BHDS) is a rare autosomal dominant inherited disease caused by germline mutations in the FLCN gene." (PMID 37170274, 2023). "The pathogenic variants responsible for Birt-Hogg-Dubé syndrome (BHDS) in folliculin (FLCN) gene mostly consist of point mutations." (PMID 37170274, 2023). "Per full gene analysis, there was found to be a positive pathogenic c.1285delC (g.17119709) in the FLCN gene, consistent with the diagnosis of Birt-Hogg-Dubé syndrome." (PMID 36895521, 2023). "Birt-Hogg-Dubé syndrome has been identified in 200 families worldwide, and although the penetrance of folliculin mutations in affected families is high, the presence of the cutaneous, renal, and pulmonary manifestations can vary." (PMID 36895521, 2023). "With the identification of FLCN c.1432 + 1G > A variant, we further reveal the etiology of recurrent pneumothorax, and confirm the diagnosis of BHD syndrome." (PMID 37417625, 2023). "We identified a heterozygous splicing mutation in the FLCN gene (c.1432 + 1G > A; rs755959303) by whole-exome sequencing analysis and made the final diagnosis of BHD syndrome, which had been delayed for 3 years since her first pneumothorax." (PMID 37417625, 2023). "Based on FLCN mutation and the family history of pulmonary cysts and pneumothorax, BHD syndrome was finally diagnosed, which had been delayed for 3 years since her first pneumothorax." (PMID 37417625, 2023).
Birt-Hogg-Dube syndrome (continued). "In our unusual case, the patient was found to harbor a FLCN germline mutation pathogenic for Birt-Hogg-Dubé syndrome." (PMID 35941667, 2022). "Birt-Hogg-Dubé syndrome (BHD) is an inherited disease caused by pathogenic variants in the FLCN gene." (PMID 36028846, 2022). "Birt-Hogg-Dubé syndrome (BHD) is a rare inherited autosomal dominant condition caused by a mutation in the tumor suppressor gene FLCN." (PMID 36338635, 2022). "Birt-Hogg-Dube syndrome is an autosomal dominant condition that arises from germline folliculin (FLCN) mutations." (PMID 35664771, 2022). "Birt-Hogg-Dubé syndrome (BHD) is a rare genetic disorder caused by germline mutations in the tumor suppressor folliculin gene (FLCN)." (PMID 36348850, 2022). "Birt-Hogg-Dubé syndrome (BHD) is a rare autosomal dominant inherited disorder caused by germline mutations in folliculin (FLCN)." (PMID 35479937, 2022). "Of note, FLCN is mutated in Birt-Hogg-Dubé syndrome patients, where RagC/D activity and downstream regulation of TFEB/TFE3 seem to be particularly affected, highlighting FLCN-Rag-mTORC1-TFEB as an important signaling axis in human disease." (PMID 35822019, 2021). "Birt-Hogg-Dubé syndrome (BHDS) is an autosomal dominant hereditary disease associated with folliculin (FLCN) gene mutation on chromosome 17." (PMID 34941164, 2021). "Birt-Hogg-Dubé syndrome (BHD) is a rare inherited autosomal dominant disorder caused by germline mutations in the tumor suppressor gene FLCN encoding the protein folliculin." (PMID 33987191, 2021). "Birt-Hogg-Dubé syndrome (BHD) is a rare autosomal dominant disorder caused by mutations in the FLCN gene coding for folliculin." (PMID 32448321, 2020). "Mutation in the human FLCN gene has been identified as the cause of Birt-Hogg-Dubé syndrome, an autosomal dominant condition characterised by early onset renal tumours, hair follicle hamartomas, pulmonary cysts and spontaneous pneumothoraces." (PMID 32216834, 2020). "Further analysis of tumors from patients with BHD syndrome revealed somatic FLCN second hit inactivating mutations in the wild-type allele, in line with FLCN having a tumor suppressor function." (PMID 33137092, 2020). "In this work, we focus on the rare FLCN missense and single codon deletion variants linked to BHD syndrome." (PMID 33137092, 2020). "Birt-Hogg-Dubé syndrome (BHDS) is an autosomal dominant inherited disorder caused by germline mutations in the folliculin (FLCN) gene, which encodes a tumor suppressor protein." (PMID 31615547, 2019). "Birt-Hogg-Dubé syndrome is an autosomal dominant hereditary condition caused by mutations in the folliculin-encoding gene FLCN (NM_144997)." (PMID 29357828, 2018). "Birt-Hogg-Dubé syndrome (BHD) is an autosomal dominant disorder caused by germline mutations in the folliculin gene (FLCN)." (PMID 29720200, 2018). "While on hemodialysis program she was diagnosed clinically with BHD syndrome and molecular testing confirmed an heterozygous mutation on FLCN gene." (PMID 30326848, 2018). "Birt-Hogg-Dubé syndrome (BHD) is a rare autosomal dominant inherited tumor syndrome caused by mutations in the FLCN gene." (PMID 28499369, 2017). "Birt-Hogg-Dube syndrome (BHD) is a rare disorder caused by mutations in the gene that encodes folliculin (FLCN) and is inherited in an autosomal dominant manner." (PMID 28151982, 2017). "Due to the strongly increased risk of renal cell carcinoma in patients with BHD syndrome and the occurrence of renal tumors in rodent models of the disease FLCN can be considered a tumor suppressor protein." (PMID 28499369, 2017). "FLCN mutations are implicated in Birt-Hogg-Dube syndrome, a disease involving fibrofolliculomas, renal tumors, lung cysts, and pneumothorax." (PMID 27120335, 2016). "Birt-Hogg-Dubé syndrome (BHD) is an inherited disorder caused by genetic mutations in the folliculin (FLCN) gene." (PMID 26974543, 2016).
Birt-Hogg-Dube syndrome (continued). "Primary spontaneous pneumothorax (PSP) or pulmonary cysts is one of the manifestations of Birt-Hogg-Dube syndrome (BHDS) that is caused by heterozygous mutations in FLCN gene." (PMID 27229674, 2016). "This is the first reported case of BHD syndrome in an Indonesian patient confirmed by detection of a FLCN exon 6 mutation." (PMID 28031834, 2016). "Germline mutations in the folliculin (FLCN) gene have been confirmed as the aetiology of BHD syndrome." (PMID 28031834, 2016). "Birt-Hogg-Dubé syndrome (BHD) is an autosomal dominant disease caused by mutations of germline folliculin (FCLN) mapped in the chromosome 17p11.2 region." (PMID 26943385, 2015). "FLCN has been shown to be a causal gene for Birt-Hogg-Dubé syndrome, which is associated with an increased risk for renal or colorectal cancers." (PMID 26109429, 2015). "Birt-Hogg-Dubé syndrome was suspected by the clinicians and later confirmed with genetic testing through GeneDx (Gaithersburg, MD) positive for the FLCN gene mutation, specifically IVS4-2 A>G, also referred to as c.250-2 A>G." (PMID 25610687, 2014). "Among these, FLCN has been suspected to be a tumor suppressor gene whose inactivation by mutations is causative of Birt-Hogg-Dubé syndrome, whose symptoms include susceptibility to renal cancers." (PMID 24670534, 2014). "Birt-Hogg-Dubé syndrome (BHD) is a rare autosomal dominantly inherited disorder caused by germline mutations in the folliculin (FLCN) gene." (PMID 24994497, 2014). "Birt-Hogg-Dubé syndrome (BHD) is a monogenic disorder caused by mutations in FLCN/Folliculin (MIM607273)." (PMID 23369289, 2013). "Mutations in FLCN cause Birt-Hogg-Dubé syndrome, an autosomal dominant disorder notable for development of cutaneous fibrofolliculomas or trichodiscomas, a variety of renal tumors, and spontaneous pneumothorax due to cystic lung changes." (PMID 23050938, 2012). "Among 27 families with clinical BHD (multiple fibrofolliculomas) evaluated at our center 22 had pathogenic FLCN mutations, resulting in a 81% yield for FLCN mutation analysis." (PMID 22146830, 2011). "Germline mutations in the folliculin (FLCN) gene are associated with the development of Birt-Hogg-Dubé syndrome (BHDS), a disease characterized by papular skin lesions, a high occurrence of spontaneous pneumothorax, and the development of renal neoplasias." (PMID 21162720, 2010). "Rare loss-of-function folliculin (FLCN) mutations are the genetic cause of Birt-Hogg-Dubé syndrome, a monogenic disorder characterized by spontaneous pneumothorax, fibrofolliculomas, and kidney tumors." (PMID 19116017, 2008). "Folliculin (FLCN) mutations have been linked to Birt-Hogg-Dubé syndrome 54-56." (PMID 40860157, 2025). "Subjects with pathogenic (PV) and likely pathogenic (LPV) FLCN variants have an increased risk of manifesting benign and malignant disorders that are related to Birt-Hogg-Dubé syndrome (BHDS): an autosomal dominantly inherited disorder whose severity can vary significantly." (PMID 37569793, 2023). "Thus, we conclude that the FLCN c.1432 + 1G > A is the major pathogenic cause of the recurrent pneumothorax in our patient, and confirm the final diagnosis of BHD syndrome." (PMID 37417625, 2023). "Folliculin (FLCN) is a tumor suppressor gene that is deficient in Birt-Hogg-Dube syndrome (BHD), a disorder that features renal carcinoma of multiple histological types including hybrid oncocytic RCC, chromophobe RCC, oncocytoma, multiple and bilateral clear cell RCC." (PMID 33643028, 2020). ", and show that the structural destabilization, conferred by the mutations, leads to rapid proteasomal degradation of the FLCN variants, and in the rare cases that BHD syndrome is triggered by such single site mutations, the disease should be considered a protein misfolding disease." (PMID 33137092, 2020). "The autosomal dominantly inherited BHD syndrome is caused by variants in the FLCN gene." (PMID 33137092, 2020).